IL6 (interleukin 6)
Diseases named in the same sentence as IL6 in open-access papers (continued):
Sharing a sentence is not in itself a finding about the gene and the disease.
COVID-19 (continued). "An elevated level of cytokines, such as interleukin (IL)-1, IL-2, IL-6, IL-8, IL-10, TNF-α, and soluble IL-2R, and a sharp inflammatory storm have been reported in patients with severe COVID-19 by our team and other researchers." (PMID 33776910, 2021). "According to recent reports, a similar immunopathologic lesion is described in severe COVID-19 cases, with enriched macrophages in lungs and elevated cytokines such as IFN-γ, IL-1, IL-6, TNF, and IL-18 in blood, accelerating the collapse of immune homeostasis." (PMID 33397398, 2021). "COVID-19 AIS patients also had significantly higher admission D-dimer level, IL-6, platelet count, procalcitonin, hemoglobin, lactate dehydrogenase, brain natriuretic peptide, and neutrophil/lymphocyte ratio." (PMID 34675873, 2021). "The patients who recovered from COVID-19 had significantly lower plasma levels of KYN, CRP, IL-6, ferritin, NTproBNP, cTnT, and creatinine." (PMID 34943063, 2021). "A significant increase in GM-CSF+ CD4 T cells with extremely high ex vivo IL-6 and IFN-γ production was reported in critically ill COVID-19 patients." (PMID 34603758, 2021). "The IHC analysis showed increased expression of caspase-1, ICAM-1, IL-1β, IL-6, MMP-9, TNF-α, and other markers in the hearts of COVID-19 patients." (PMID 34804033, 2021). "A recent study analyzed 671 severe cases of non-COVID-19 bacterial and viral pneumonia and 2910 nonserious cases of bacterial and viral pneumonia by identifying a significant association of the IL-6-174C allele (associated with a level of IL-6 plus elevated) with the severity of pneumonia." (PMID 34829918, 2021). "Consequently, a role for GSH in modulating IL-6 mediated cascade in COVID-19 may be hypothesized." (PMID 33808471, 2021). "In particular, Gal-9, IL-6, IP-10, IL-10, and TNF-α were substantially higher in COVID-19 patients versus HCs." (PMID 33947753, 2021). "In mild vs critical COVID-19, we observed that amongst several other pathways, IFN- (type I and II), interleukin (e.g., IL12 and IL6) and oligoadenylate synthetase (OAS) antiviral response signaling was increased in CD8+ TRM- and TEX-lineages." (PMID 33473155, 2021). "Regarding the mild B COVID-19 subgroup, it was observed significant positive correlations between IFN-α and IFN-γ, and also between these interferons and IL-6 and IL-10." (PMID 33717074, 2021). "Among them, IL6, tumor necrosis factor alpha (TNFα), MAPK1, MAPK14, MAPK8, PTGS2, IL2 and PPARG were the predominant targets for Xuebijing to treat COVID-19." (PMID 34539389, 2021). "A recent study demonstrated that active caspase-1 (Casp1p20), IL-1β, IL-18, IL-6, and lactate dehydrogenase (LDH) were increased in the serum of patients with COVID-19, and that Casp1p20 and IL-18 are products derived from inflammasomes." (PMID 34025433, 2021). "Our COVID-19 patients had significantly higher levels of IL-1β, IL-1Ra, IL-10, IFN-α2, IL-6, IL-18, and TNF-α than HC." (PMID 34367188, 2021). "Recent work indicated that critically ill COVID-19 patients had marked elevations of serum levels of ACE2, ferritin, and IL-6." (PMID 34067683, 2021). "Here, we present an analysis of IL-6 levels related to several aspects of SARS-CoV-2 infection in 1,472 patients with COVID-19, hospitalized at the Wuhan Huoshenshan Hospital." (PMID 33746945, 2021). "The National Health Commission of the People's Republic of China included elevated inflammatory factors such as IL-6 and CRP aspotential early warning indicators of severe disease in its widely used "COVID-19 diagnosis and treatment plan"." (PMID 35539890, 2021). "MHD patients with COVID-19 had elevated infection-related biomarkers, including CRP, ESR, procalcitonin, IL-6, IL-2R and TNF-α, which likely reflected an exacerbated inflammatory response." (PMID 33967613, 2021). "It was reported that plasma cytokines IFN-γ, IL-10, IL-12p70, IL17A, IL-6 and TNF-α levels are increased in COVID-19 patients admitted to the ICU when compared with healthy controls." (PMID 34289718, 2021).
COVID-19 (continued). "A variety of proinflammatory cytokines, such as IL-1β, IL-6, IL-8, and IFN-γ, were elevated in severe COVID-19 patients and active AOSD patients, suggesting a common link of the cytokine storm in the pathogenesis of both diseases." (PMID 34239943, 2021). "detected 10 cytokines (including IFN-γ, IL-1α/β, IL-2, IL-6, IL-15, IL-18, IL-33, and TNF-α/β) that were upregulated in patients with moderate or severe COVID-19 compared with the samples from healthy individuals." (PMID 34737743, 2021). "However, the production of IL-6 could be a normal reaction of the host defense in COVID-19." (PMID 35095877, 2021). "The levels of IL1-β, IL-6, IL-8 (p < 0.0001, for each), and TNF-α (p < 0.01) were significantly higher in the critical COVID-19 patients than in the mild COVID-19 and non-COVID-19 healthy controls." (PMID 34276659, 2021). "Elevated VWF antigen and activity levels have been documented in COVID-19.9, 11, 20Likewise, inflammatory markers such as CRP and IL-6 are known to be elevated in COVID-19." (PMID 33709050, 2021). "The increase in blood concentrations of different cytokines such as interleukins and chemokines such as IL-6, IL-8, IL-10, TNF-α, IL-1β, IL-2, IP-10, MCP-1, CCL3, CCL4, and CCL5 has been described for COVID-19 patients." (PMID 34262570, 2021). "One study involving COVID-19 patients with hypertension found that ACE-inhibitors and Ang II type 1 receptor blockers (ARBs) reduced inflammatory cytokine production and IL-6 levels in peripheral blood." (PMID 34452063, 2021). "IL-6, IL-8 and TNF-α concentrations were significantly lower in COVID-19 groups compared to burn patients." (PMID 33921604, 2021). "The levels of interleukin (IL)-6 and monocyte chemoattractant protein 1 (MCP-1) were increased in COVID-19-positive patients." (PMID 34960751, 2021). "Levels of pro-inflammatory (IFN-γ, IL-1β, IL-6, IL-9, IL-12p70, CCL11) and anti-inflammatory (IL-4, IL-5, IL-10, IL-13) cytokines, as well as VEGF, were higher in severely ill COVID-19 patients as compared to pandemic influenza A(H1N1) subjects." (PMID 33995342, 2021). "At baseline, significant higher levels of IL-6, IL-8, and MIP-1β were observed in patients with severe disease compared with those with mild/moderate COVID-19." (PMID 34835384, 2021). "Chemokines (e.g., IL-8) dominate the BALF profile in moderate cases of COVID-19, whereas cytokines (e.g., TNF-α, IL-6) are prevalent in more severe cases." (PMID 34178722, 2021). "Ferritin, D-dimer, CRP, NLR, cytokine (IL-18 and IL-10), and cytokine receptor (IL-6, IL1-Ra, and sCD25) test results combined with clinical data can contribute to the early identification of critical COVID-19 patients." (PMID 34422145, 2021). "The levels of circulating IL-6 and MCP-1 were significantly elevated in COVID-19-positive patients when compared to COVID-19-negative patients." (PMID 34960751, 2021). "The UC-MSC treatment group is characterized by a reduction in the levels of inflammatory molecules, including IFN-γ, IL-6, and TNF-α cytokines, and regulated on activation, normal T cell expressed and secreted chemokine (RANTES) in COVID-19 patients." (PMID 34315546, 2021). "Inflammatory cytokines, such as IL-6, IL-1β, and IFN-γ that are elevated in the biospecimen of COVID-19 patients, can activate the Janus kinase (JAK)/signal transducer of activators of transcription (STAT) JAK/STAT pathway and induce the NF-kB signaling." (PMID 33917321, 2021). "Numerous studies have shown that hyperinflammation and cytokine storms, as well as increased levels of pro-inflammatory cytokines IL-6, -8, -2, -10, TNF-α, and IFN-α, correlate with the severity of COVID-19 and poor outcomes." (PMID 34603758, 2021). "Individuals in cohort one with acute COVID-19 had coagulopathy (with increased D-Dimer and fibrinogen), a marked pro-inflammatory response (elevated CRP, IL-6, TNF-α, IL-8 and IL-1β) and lymphopenia, with an increase in the neutrophil: lymphocyte ratio." (PMID 34025675, 2021).
COVID-19 (continued). "So far, it is the first clinical study investigating the role of circulating inflammatory and nociceptive molecules such as HMGB1, NLRP3 inflammasome, IL-6, IL-10, angiotensin II, and ACE2 in COVID-19 headache." (PMID 34384355, 2021). "The prognostic value of IL-6, IL-15, sRAGE, IP10, and MCP3 to predict a poor COVID-19 outcome is consistent with the observation of an exacerbated innate inflammatory response in patients with severe disease." (PMID 34829906, 2021). "A recent study on assessment of MSC therapy's efficacy and safety in COVID-19 management revealed that inflammatory indices such as WBC, pro-calcitonin, CRP and IL-6 were unchanged after MSC perfusion; IgG and IgM were also unchanged after MSC therapy." (PMID 34812049, 2021). "During the early stage of the pandemic, the upregulation of many cytokines, including interleukin (IL)-6, IL-1β, tumor necrosis factor α (TNF-α), and interferons, was observed in patients with COVID-19." (PMID 34001144, 2021). "Lymphopenia, increased neutrophil count, and gradually increasing IL-6, C-reactive protein (CRP), troponin, and ferritin levels were all present in patients with more severe forms of COVID-19." (PMID 33841446, 2021). "This was in contrast to the levels of sensitive markers of inflammation, including IL-6 and LDH, which normalized in post–COVID-19 to levels of those in healthy donors, consistent with resolved acute inflammation." (PMID 34143756, 2021). "Our study found that levels of plasma gp96 and IL-6 were closely correlated in COVID-19 patients that and gp96 can act as DAMP to activate CD14+ cells to secrete IL-6." (PMID 34817280, 2021). "SGLT2Is play a role in COVID-19 management through the upregulation of protective ACE2, the attenuation of CS through the inhibition of IL-6 release, cytoprotective effect through the improvement of cell oxygenation, and reduction of lactate formation." (PMID 34124187, 2021). "In contrary, some important cytokines in COVID-19 cytokine storm such as CXCL10, IL-6, CCL2, CCL20, IL-8 and S100A9 showed a trend of slightly lower levels in patients with asthma in all three COVID-19 severity groups." (PMID 34238349, 2021). "Several cytokines including interleukin (IL)-6, IL-10, interferon-γ (IFN-γ), and tumor necrosis factor-α (TNF-α) have been observed to increase dramatically during acute infection in COVID-19 patients." (PMID 34307393, 2021). "We also sorted the inflammatory signaling pathways in COVID-19-related ARDS, including those of IL-6/JAK/STAT, interferon, NF-κB, TLRs, Bruton’s tyrosine kinase, and renin–angiotensin system, and 49 target genes were included for further analysis." (PMID 35401158, 2021). "The serum level of interleukin 6 (IL6) increases in both DKA and COVID-19 and can be used as a prognostic factor." (PMID 34777880, 2021). "As epithelial cells and macrophages are the main producers of IL-6 in the lung, elevated IL-1RA expression may further augment IL-6 production by these cells; thereby, contributing to a deleterious positive feedback loop within COVID-19 patients that can directly impact both the lung and kidney." (PMID 34131192, 2021). "JAK2 inhibitor Fedratinib has been proved to inhibit the production of several Th17 cytokines, including IL-6, IL-17, IL-21, IL-22, IL-1β, and TNF-α, thereby preventing Th17-related cytokine storm in COVID-19 patients." (PMID 34650550, 2021). "COVID-19 patients with headache and pulmonary infiltration (n = 31) had significantly higher serum levels of HMGB1, IL-6, D-dimer." (PMID 34384355, 2021). "Plasma ATX levels have been recently reported to correlate with IL-6 levels in severe ARDS patients, as well as acute-on-chronic liver failure (ACLF) patients, as shown here in the serum of ICU COVID-19 patients." (PMID 34576169, 2021).
COVID-19 (continued). "Meanwhile, COVID-19 displayed an immune profile distinguished by increased Th1 (IL-12, IFN-γ) and Th2 (IL-4, IL-5, IL-10, IL-13) cytokine levels, along with IL-1β, IL-6, CCL11, VEGF, TWEAK, TSLP, MMP-1, and MMP-3." (PMID 33995342, 2021). "Patients with COVID-19 have a large number of pro-inflammatory cytokines (CXCL-8, IL-6, CCL3, CCL4, and IL-12) due to human alveolar epithelial cells with dysfunctional mitochondria." (PMID 34360945, 2021). "Elevated levels of inflammatory cytokines such as IL-6 and TNF-α have also been shown in the CSF of COVID-19 patients with neurological presentation, indicating an ongoing inflammatory process in the brain." (PMID 34680490, 2021). "Several investigators reported a negative correlation between T cell numbers and the concentration of cytokines including interleukin-6 (IL-6), IL-10, interferon-γ (IFN-γ), and tumor necrosis factor-α (TNF-α) in COVID-19 patients." (PMID 34522871, 2021). "We observed that the levels of inflammation indicators in severe COVID-19-infected patients, including ESR, CRP, and IL-6, were significantly increased." (PMID 34222271, 2021). "Blood levels of IL-6 and lactate dehydrogenase (LDH) are independent predictors of COVID-19 severity." (PMID 34299225, 2021). "Pro-inflammatory cytokines IL-6, IL-8 and TNF-α are responsible for the cytokine storm in COVID-19 patients, leading to impairment of oxygen diffusion, pulmonary fibrosis and eventually multiple organ failure." (PMID 34885798, 2021). "In our cohort, we observed that serum levels of IL-6 and TNF-α were more elevated at diagnosis in children affected by COVID-19 compared with other infectious diseases." (PMID 34578450, 2021). "In the event of severe lung infection due to COVID-19, hyper-production of inflammatory markers such as IFN-γ, TNFα, IL-1, IL-6, and IL-12 are evident." (PMID 34066983, 2021). "Overall, our study demonstrates that, in association with clinical observations, the kinetic measurement of IL-6 during SARS-CoV-2 infection is a crucial tool to predict the prognosis, response to therapy, and outcome of patients with COVID-19." (PMID 33679753, 2021). "In other studies, while IL-6, IL-8 and TNF-α were significantly raised above their normal levels among COVID-19 ARDS patients, the increases were significantly less than in non-COVID ARDS or sepsis patients." (PMID 33672738, 2021). "In our cohort of moderately and severely sick hospitalized COVID-19 patients, IL-6, MIG, TNF-α, IL-8, IL-18 and IP-10 were highest in patients with severe COVID-19." (PMID 34539644, 2021). "Regarding inflammation biomarkers, our results showed that IL-6, PSEP and calprotectin concentrations significantly increased with severity in COVID-19-patients." (PMID 34299080, 2021). "SARS-CoV-2 is known to induce the production of significant amounts of pro-inflammatory cytokines and mediators, such as IL-1, IL-6, and vascular endothelial growth factor (VEGF), which results in a cytokine storm in severe COVID-19 cases." (PMID 34202029, 2021). "Taken together, these data indicate that the exogenous rhGal-9 exhibits a stimulatory function by enhancing the production of proinflammatory cytokines (e.g., IL-6 and TNF-α as the major monocyte-derived cytokines) in COVID-19 patients." (PMID 33947753, 2021). "Our further analysis confirmed a positive correlation of the plasma Gal-9 concentration with IL-6, TNF-α, IP-10, MIP-1α, and MCP-1 in COVID-19 patients." (PMID 33947753, 2021). "Increased IL-2, IL-6, TNF-α, and IFN-γ were detected in trophoblast cells and maternal blood of COVID-19 placentas." (PMID 35071136, 2021). "Patients with MIS-C showed higher plasma levels of C reactive protein (CRP), MPO, IL-6, and of the pro-inflammatory chemokines CXCL8 and CCL2 than COVID-19 children." (PMID 33841438, 2021). "IFN-γ was lower in the SEVERE COVID-19 group when compared to COVID-19 MILD, while pro-inflammatory cytokine levels (IL-6, TNF-α, and MCP-1) were higher." (PMID 34315957, 2021).
COVID-19 (continued). "Higher levels of interleukin IL-6 and IL-10, and lower levels of CD4+T and CD8+T are also observed in patients with COVID-19 and these correlate with the severity of disease." (PMID 33643932, 2021). "The analysis results showed that the serum Ca2+ of COVID-19 patients was significantly negatively correlated with PCT, calcitonin, D-dimer, PFDP, ESR, CRP, and IL-6." (PMID 34222271, 2021). "Compared with patients in severe COVID-19, those who in critical COVID-19 had significantly higher levels of tumor necrosis factor-α (TNF-α), interleukin-6 (IL-6), IL-8, and IL-10." (PMID 34725309, 2021). "In the validation cohort, IL-6 and GDF-15 were elevated in COVID-19 and sepsis on day 1, and the levels of these cytokines were higher in sepsis than in COVID-19." (PMID 35095877, 2021). "Compared with HC, IL-18, IL-6, and ferritin were markedly elevated in active AOSD patients (Log2 fold changes, 8.86, 8.34, and 4.30, respectively) and in severe COVID-19 patients (Log2 fold changes, 2.73, 6.97, and 1.97, respectively)." (PMID 34367188, 2021). "Accordingly, the results of the present study demonstrated that patients with severe COVID-19 had higher levels of several inflammatory biomarkers (e.g., NLR, CRP, procalcitonin, PCT, IL-6, and IL-10 levels)." (PMID 33763027, 2021). "Cytokine storm mediated by proinflammatory cytokines such as interleukin-6 (IL-6) and tumor necrosis factor-alpha (TNF-α) is probably the culprit for severe COVID-19." (PMID 34178527, 2021). "Regarding the pathway enrichment analysis, the present study shows that the IL-17, IL-6, TNF-α, and IFN signals, complement system, and growth factor receptor signaling were major pathways by which GA targets COVID-19." (PMID 34177566, 2021). "For example, interferon-inducible protein-10 and IL-6 are predictive factors for SARS and COVID-19 outcomes, respectively; yet, they were excluded." (PMID 34158873, 2021). "Increased cardiac adipose tissue index and IL-6 relate significantly to early mortality and ICU requirement in COVID-19 patients with diabetes." (PMID 34384426, 2021). "Inflammatory parameters (IL-6, IL-10, TNF-alpha, IFN-gamma, MCP-1) were increased in COVID-19 patients with severe illness." (PMID 35136584, 2021). "A previous study that examined circulating cytokine levels from people with severe COVID-19 showed a decrease in IFN-γ and increased IL-6, CXCL8, IL-1β, and CCL2, as compared to healthy controls." (PMID 34108966, 2021). "Several pro-inflammatory cytokines, including interleukin-6 (IL6), tumor necrosis factor-alpha (TNF-α), and transforming growth factor-beta (TGF-β), contribute to the inflammatory injury of lungs in COVID-19 patients during the CRS." (PMID 33815126, 2021). "Individuals with severe COVID-19 have markedly reduced numbers of CD4+ and CD8+ T cells, and lymphocyte counts negatively correlate with levels of serum IL-6, IL-10, and TNF-α." (PMID 34440767, 2021). "And in agreement with previous studies, we observed an increase in the levels of plasma IL-6, C-reactive protein (CRP) and ferritin in COVID-19 patients in comparison with HC." (PMID 33777054, 2021). "For instance, COVID-19 presents with fever, ARDS, and elevated immune marker levels in sera, such as interleukin (IL-6)." (PMID 34564316, 2021). "As expected, the inflammatory markers white blood cell (WBC) count and IL-6 were higher in ARDS and COVID-19 compared to control and COPD." (PMID 34573092, 2021). "Further analysis indicated that cystatin C was negatively correlated with IL-6 (r=− 0.472, P=0.001) and eGFR was inversely correlated with CRP (r=− 0.210, P=0.012) among COVID-19 patients." (PMID 33557785, 2021). "Increased expression of the cytokines IL-6, IL-10, and TNF-α is closely related with severe COVID-19." (PMID 34484133, 2021). "C3a, C5a, and factor P (properdin), as well as interleukin (IL)-1β, IL-6, IL-8, tumor necrosis factor (TNF)-α, and IgM antibody levels, were higher in critical COVID-19 patients compared to mild COVID-19 patients." (PMID 34276659, 2021).